TSPAN31 (tetraspanin 31)
Synonyms: SAS
Tractability: Antibody: its Gene Ontology location is reachable by antibodies, with high confidence; UniProt predicts a signal peptide or a membrane-spanning region. PROTAC: its protein half-life has been measured.
Gene: Protein-coding gene on chromosome 12 (57,738,013 to 57,750,219, forward strand). Ensembl gene ENSG00000135452.
Subcellular location: Membrane
Subcellular location (Human Protein Atlas): Golgi apparatus; Cytokinetic bridge; Cytosol; Nucleoplasm
Gene Ontology:
Molecular function: protein binding
Biological process: positive regulation of cell population proliferation
Cellular component: membrane; plasma membrane
Genetic constraint (gnomAD): Loss-of-function variants: 16 observed, 26.31 expected, observed/expected ratio (o/e) 0.61, 90% interval 0.41 to 0.92. The upper end of that interval is the gene's LOEUF score, 0.92, which puts it in group 3 of 6, group 1 being the genes least tolerant of losing a copy. Missense variants: 209 observed, 260.88 expected, observed/expected ratio (o/e) 0.8, 90% interval 0.71 to 0.9. Synonymous variants: 87 observed, 93.85 expected, observed/expected ratio (o/e) 0.93, 90% interval 0.78 to 1.11.
Homologues: Orthologues: macaque TSPAN31 (99% identical), chimpanzee TSPAN31 (99% identical), dog TSPAN31 (97% identical), pig TSPAN31 (94% identical), guinea pig TSPAN31 (89% identical), mouse Tspan31 (88% identical), rabbit TSPAN31 (85% identical), rat Tspan31 (83% identical), tropical clawed frog tspan31 (71% identical), zebrafish tspan31 (71% identical). Paralogues in human: TSPAN13 (57% identical), CD63 (25% identical), TSPAN17 (23% identical), TSPAN8 (23% identical), TSPAN9 (23% identical), CD82 (23% identical), TSPAN4 (23% identical), CD37 (22% identical), TSPAN18 (22% identical), CD9 (22% identical), TSPAN3 (22% identical), TSPAN33 (22% identical), and 20 more.
Diseases named in the same sentence as TSPAN31 in open-access papers:
TSPAN31 is named in the same sentence as 18 diseases in open-access papers, as found by Europe PMC text mining. Sharing a sentence is not in itself a finding about the gene and the disease. The quoted sentences say what the papers report.
gastric cancer (4 papers, 2022 to 2024). A primary or metastatic malignant neoplasm involving the stomach. "Tspan31 facilitated the proliferation and metastasis of gastric cancer through METTL1/CCT2 and PI3K/AKT." (PMID 38649381, 2024). "TSPAN31 is highly expressed in gastric cancer tissues and correlates with poor prognosis of gastric cancer patients." (PMID 36941633, 2023). "Knockdown of TSPAN31 improves chemosensitivity to cisplatin through the suppression of ABCC2 in gastric cancer cells." (PMID 36941633, 2023). "Likewise, in gastric cancer, Tspan31 has an anti-apoptotic function, as the level of apoptosis in gastric cancer cells was significantly increased after upregulation of Tspan31 expression and significantly decreased after downregulation of Tspan31 expression." (PMID 38649381, 2024). "In gastric cancer, Tspan31 was found to be upregulated in tumor tissues, and silencing Tspan31 effectively inhibited migration and proliferation of GC cells by impairing the METTL1/CCT2 pathway." (PMID 38389703, 2024). "It has also been shown that TSPAN31 is highly expressed in gastric cancer (GC) tissues and that a high expression of TSPAN31 leads to a poor prognosis in GC patients." (PMID 36119498, 2022).
hepatocellular carcinoma (4 papers, 2020 to 2024). A malignant tumor that arises from hepatocytes. "Tspan31 promotes proliferation and motility in hepatocellular carcinoma via the AKT/GSK-3β/β-catenin pathway." (PMID 38649381, 2024). "In contrast, TSPAN31 facilitates the migration and invasion, but has less impact on proliferation of hepatocellular carcinoma cells." (PMID 36941633, 2023). "TSPAN31 serves as a natural antisense transcript to inhibit CDK4 protein expression in human cervical cancer and hepatocellular carcinoma by targeting the 3ʹ-untranslated region of the CDK4 mRNA, thus suppressing cell proliferation." (PMID 36941633, 2023). "As a natural antisense transcript of cyclin-dependent kinase 4 (CDK4), TSPAN31 regulates the expression of CDK4 mRNA and protein in hepatocellular carcinoma cells (HCC)." (PMID 32507938, 2020). "For example, TSPAN31 has been reported to promote migration of hepatocellular carcinoma, but not affect cell proliferation." (PMID 36941633, 2023).
glioma (2 papers, 2021 to 2024). A benign or malignant brain and spinal cord tumor that arises from glial cells (astrocytes, oligodendrocytes, ependymal cells). "Six of those genes were found in three of the six most enriched ‘glioma TADs’: 2160 (CDK4, TSFM, TSPAN31, B4GALNT1), 2337 (NFATC4) and 2688 (CACNA1G)." (PMID 34341417, 2021).
osteosarcoma (2 papers, 2020 to 2022). A usually aggressive malignant bone-forming mesenchymal neoplasm, predominantly affecting adolescents and young adults. "In addition, there is one report concerning TSPAN31 (tetraspanin 31) and lung metastasis happened in osteosarcoma." (PMID 33378415, 2020).
breast carcinoma (1 paper, 2020). "Finally, 6 genes (GOLGB1, TMEM158, CXCL8, MCM5, HIF1AN, and TSPAN31) were selected that could optimally predict the lung metastasis risk of breast cancer patients." (PMID 33378415, 2020).
cervical cancer (1 paper, 2024). A primary or metastatic malignant neoplasm involving the cervix. "Likewise, in cervical cancer, Tspan31 directly silences CDK4 by targeting its 3′-untranslated region (3′-UTR), a master switch controlling cell cycle progression." (PMID 38649381, 2024). "Tspan31 directly silences CDK4, a master switch controlling cell cycle progression, by targeting its 3′-untranslated region (3′-UTR) in cervical cancer, highlighting its ability to modulate cell cycle checkpoints." (PMID 38649381, 2024).
liposarcoma (1 paper, 2015). A usually painless malignant tumor that arises from adipose tissue. "The most evidence, to date, demonstrates an oncogenic role in dedifferentiated liposarcoma, like the atypical lipomatous tumor/well-differentiated liposarcoma, for MDM2, CDK4, HMGA2, and TSPAN31 (SAS)." (PMID 25713799, 2015).
metastatic tumor (1 paper, 2024). "The TSPAN13, TSPAN31, and UPK1B genes were upregulated in the fibroblast compartment of metastatic tumor." (PMID 38255741, 2024). "The upregulation of TSPAN13, TSPAN31, and UPK1B genes in the fibroblast compartment of metastatic tumor suggests their potential significance in the context of tumor–fibroblast interactions, metastasis, and the distinct characteristics of the metastatic microenvironment." (PMID 38255741, 2024).
ovarian carcinoma (1 paper, 2022). A malignant neoplasm originating from the surface ovarian epithelium. "Notably, TSPAN31 is also involved in the activation of Akt signaling pathway, a key regulator of survival in ovarian cancer, also associated with chemoresistance." (PMID 35120576, 2022).
sarcoma (1 paper, 2025). A usually aggressive malignant neoplasm of the soft tissue or bone. "Twenty-two genes were essential for at least one sarcoma cell line, with some being more selective for specific STS, like TSPAN31 for LPS." (PMID 40814001, 2025).
tumor (7 papers, 2009 to 2024). "Splice variants generated with some of those specific intron junctures in CD82 and TSPAN 32 from group CD63L have been reported in normal and tumor tissues and from TSPAN17, TSPAN 31 from groups TSPAN15L and TSPAN13L (mRNA variants hApr07 and jApr07 from NCBI AceView) respectively." (PMID 19262691, 2009). "The co-amplification of HMGA2, TSPAN31, and YEATS4 with MDM2 is frequently observed in DDLPS and is involved in tumor development." (PMID 34834427, 2021). "Some tetraspanins, such as TSPAN15, can enhance tumor cell proliferation ability, while other family members, such as CD9, CD63, TSPAN1, TSPAN7, and TSPAN31, can antagonize apoptosis and facilitate tumor cell survival." (PMID 34540692, 2021). "Whole-exome sequencing showed that this tumor also harbored CDK4, TSPAN31, and JUN amplification." (PMID 37881487, 2023).
cancer (2 papers, 2022 to 2023). A tumor composed of atypical neoplastic, often pleomorphic cells that invade other tissues. "TSPAN31, recently discovered to be linked to cancer, as natural antisense transcript of cyclin dependent kinase 4 (CDK4), regulates the expression of CDK4 mRNA and protein." (PMID 35120576, 2022). "CD81, CD9, TSPAN31, and TSPAN13 are also reported to facilitate cancer cell invasion and metastasis." (PMID 36941633, 2023). "TSPAN1, TSPAN3, TSPAN12, TSPAN31, CD82 and CD63 have also been reported to reduce chemosensitivity of cancer cells." (PMID 36941633, 2023). "The following TSPANs have been involved in enhancing cancer therapy resistance: CD9, CD81, TSPAN1, TSPAN3, TSPAN31, CD82 and CD63." (PMID 36941633, 2023). "Altogether, TSPAN1, TSPAN15, TSPAN29, and CD151 could support cancer cell growth, while TSPAN31, TSPAN6, CD9, CD37 could inhibit cancer growth." (PMID 36941633, 2023).
digestive system cancer (1 paper, 2024). A primary or metastatic malignant neoplasm involving any part of the digestive system. "Generally, the expression of CD9, CD151, Tspan1, Tspan5, Tspan8, Tspan12, Tspan15, and Tspan31 are upregulated, facilitating the migration and invasion of digestive system cancer cells." (PMID 38389703, 2024).
TSPAN31 also shares sentences with these, for which no sentence is quoted: autoimmune disorders (1 paper); bone tumor (1); colorectal cancer (1); gynecologic cancer (1); retinal degeneration (1).